CTSD (cathepsin D)
Diseases named in the same sentence as CTSD in open-access papers (continued):
Sharing a sentence is not in itself a finding about the gene and the disease.
colitis (5 papers, 2021 to 2024). Inflammation of the colon. "Inhibition of both CTSB and CTSD has been shown to ameliorate DSS colitis and overexpression of MMP-9 to aggravate DSS and infectious colitis." (PMID 39200138, 2024). "Further research is necessary to explore if this increased cathepsin D expression in acute colitis affects inflammation and pain by the degradation of β-endorphin." (PMID 34639054, 2021). "In experimental murine models of colitis, dietary sphingomyelin exacerbated mucosal damage, colonic inflammation, and intestinal epithelial cell apoptosis in a manner suggestive of ceramide activation of the lysosomal cell death moderator cathepsin D." (PMID 35751094, 2022). "Furthermore, the inhibition of cathepsin D ameliorated inflammatory scores in the acute DSS colitis mouse model." (PMID 34639054, 2021). "Inhibition of cathepsin D was followed by amelioration of mouse dextran sodium sulfate (DSS) colitis; the level of anti-cathepsin G antibodies was significantly higher in patients with severe colitis than in those with mild or moderate colitis (p < 0.05)." (PMID 39359476, 2024).
dementia with Lewy body (5 papers, 2015 to 2024). "CTSD protein and activity are reduced in the frontal cortex of PD and Lewy body dementia brains with GBA1 mutation." (PMID 31634558, 2020). "Given the similarities to the GBA1 studies, our current results suggest that the reduced expression of CTSD leads to accelerated disease progression in Lewy body diseases." (PMID 26448324, 2015). "In addition, the activities of lysosomal enzymes, such as GCase and the protease cathepsin D, were decreased in the SNpc and frontal cortex of patients with PD and patient with dementia of Lewy body." (PMID 38388451, 2024). "Decreased CTSD activity has been found in brains of PD and dementia with Lewy body patients with and without GBA1 variants and correlated with both reduced GCase activity and GBA1 gene expression." (PMID 35179198, 2022). "Decreased CTSD activity has been reported in brains of PD and dementia with Lewy body patients with and without GBA1 mutation, and correlated with both reduced GCase activity and GBA1 gene expression." (PMID 31634558, 2020). "SUMO1-positive inclusions have been reported for multiple system atrophy (MSA), diffuse Lewy body disease (DLB) and PSP where it is found in lysosomal compartments based on cathepsin D co-localization." (PMID 35567706, 2022).
endothelial dysfunction (5 papers, 2013 to 2025). In vascular diseases, endothelial dysfunction is a systemic pathological state of the endothelium (the inner lining of blood vessels) and can be broadly defined as an imbalance between vasodilating and vasoconstricting substances produced by (or acting on) the endothelium. "We demonstrated that SCU, via upregulation of CTSD levels in endothelial cells, rescued autophagy-lysosomal function and alleviated I/R-mediated endothelial dysfunction." (PMID 40098620, 2025). "Mechanistically, our data indicate that SCU can resist endothelial dysfunction by increasing lysosomal flow and autophagic flux, the effects of which are mediated by the direct upregulation of cathepsin D (CTSD) levels and its activity." (PMID 40098620, 2025). "In PPCM, oxidative stress is thought to trigger cathepsin D to cleave 23‐kDa prolactin into a 16‐kDa fragment, which leads to endothelial dysfunction through the up‐regulation of miRNA‐146a." (PMID 40654268, 2025). "Consistently, cathepsin D levels are reported to negatively correlate with endothelial dysfunction in chronic kidney disease." (PMID 29375176, 2017). "Taken together, this study demonstrates that CFTR upregulation protects against PA-induced endothelial dysfunction through improving autophagic flux with an underlying mechanism being involved in enhancing Atg12-Atg5-Atg16L complex formation and restoring the CTSB and CTSD protein expression." (PMID 33123317, 2020). "Moreover, increased plasma levels of Cathepsin D, ADMA and miRNA-146a support the hypothesis that a circuit involving Prolactin cleavage and subsequent endothelial dysfunction acts as a major pathophysiological concept for this disease." (PMID 23812247, 2013).
epilepsy (5 papers, 2014 to 2025). A brain disorder characterized by episodes of abnormally increased neuronal discharge resulting in transient episodes of sensory or motor neurological dysfunction, or psychic dysfunction. "We also measured expression levels of cathepsin D to analyze the participation of lysosomal proteases in the mechanism of cell death caused by epilepsy induced by pilocarpine." (PMID 33919533, 2021). "Patients with epilepsy, growth retardation, dysmorphic features, multi-system involvement (bone abnormalities, myelodyplasia, albuminuria) and unexplained biochemical findings such as cobalamin deficiency and partial cathepsin D deficiency should be considered at risk." (PMID 25233840, 2014). "According to the ROC curves, the expression level of key genes including CTSD, CREG1, PECAM1, ZNF101, RRM2B, MARCKSL1, and MAP2K4 demonstrated a certain accuracy in classifying epilepsy and control groups (0.7 < AUC < 0.9)." (PMID 40520613, 2025). "CtsD-CKO mice also develop a severe pathological phenotype that manifests as neurological symptoms and progressively exhibit a kinetic epilepsy like phenotype." (PMID 35804072, 2022). "Fifteen potential key genes in epilepsy were identified, including RPS6KA3, CTSD, and NCAM1." (PMID 40520613, 2025).
Hepatic steatosis (5 papers, 2016 to 2021). Steatosis is a term used to denote lipid accumulation within hepatocytes. "Recently, we showed that extracellular CTSD inhibition led to reduced hepatic steatosis and insulin sensitivity in rats." (PMID 34335574, 2021). "Among these targets, cathepsin D (CTSD), was implicated as a pivot mediator in adipogenesis, lipid metabolism in mouse hepatic steatosis, mitochondrial dysfunction, cell death, and macrophage infiltration, in hypertrophic adipose tissues of genetically and HFD-induced obese mouse models." (PMID 32471061, 2020). "Moreover, we recently found that inhibition of extracellular CTSD activity reduced plasma insulin levels and hepatic lipids in rats with hepatic steatosis." (PMID 33101209, 2020). "The impact of HFD CTD-002-treated HFD-fed SD rats showed a significant reduction in the amount of fat vesicles relative to control HFD-fed rats, demonstrating the therapeutic benefit of extracellular CTSD inhibition in the context of hepatic steatosis, a main feature of NAFLD." (PMID 31060228, 2019). "Similar to these observations, we have previously shown that CTSD plays a central role in lipid metabolism during NASH and that its inhibition reduces hepatic steatosis by biliary cholesterol elimination." (PMID 34335574, 2021). "The lysosomal enzyme, cathepsin D (CTSD) has been implicated in the pathogenesis of non-alcoholic steatohepatitis (NASH), a disease characterised by hepatic steatosis and inflammation." (PMID 34335574, 2021).
Huntington disease (5 papers, 2021 to 2025). Huntington disease (HD) is a rare neurodegenerative disorder of the central nervous system characterized by unwanted choreatic movements, behavioral and psychiatric disturbances and dementia. "Cathepsin D (CTSD), a marker of lysosomes, participates in autophagy-lysosomal pathway in Huntington’s disease, and previously reported to be elevated in ASD." (PMID 40779003, 2025). "In a cell model related to Huntington’s disease, treatment with ATT reinforced the degradation of the mutant huntingtin proteins by increasing cathepsin D maturation and autophagy flux." (PMID 40427621, 2025).
ischemia (5 papers, 2016 to 2022). A hypoperfusion of the BLOOD through an organ or tissue caused by a PATHOLOGIC CONSTRICTION or obstruction of its BLOOD VESSELS, or an absence of BLOOD CIRCULATION. "CTSD has been shown to increase sharply after ischemia but will decrease as lysosomes rupture." (PMID 36151369, 2022). "Consistent with previous research, we found that the expression of LAMP-1 did not change significantly after ischemia, but cathepsin D expression was remarkably increased." (PMID 32519067, 2020).
leukemia (5 papers, 2020 to 2025). A malignant (clonal) hematologic disorder, involving hematopoietic stem cells and characterized by the presence of primitive or atypical myeloid or lymphoid cells in the bone marrow and the blood. "We show that CTSD knockdown in leukemia cells suppresses cell proliferation and the anti-apoptotic effects in vitro and alleviates AML progression in vivo." (PMID 40796615, 2025). "Conversely, in the whole lysate, CTSB was expressed in a mature form in all leukemia cells, while CTSD was expressed mainly as mature, with few amounts present in an immature form in each of the cell lines." (PMID 41227296, 2025). "Collectively, these findings indicate that the anti-AML efficacy of N-8 is CTSD-dependent, effectively inhibiting proliferation and inducing apoptosis in leukemia cells with high CTSD expression." (PMID 40796615, 2025). "Our study found that CTSD knockdown promoted apoptosis in leukemia cells by inducing the degradation of the anti-apoptosis proteins BCL2, BCL-XL, and MCL1." (PMID 40796615, 2025). "CTSD knockdown led to reduced leukemia cell infiltration and increased apoptosis in the PB, BM, and spleen." (PMID 40796615, 2025). "CTSD-siRNA U937 cells induced the apoptosis of leukemia cells, whereas CTSD overexpression effectively reversed this effect, reducing apoptosis in the same context." (PMID 40796615, 2025). "Collectively, our study reveals the role of CTSD in leukemia progression and highlights targeting CTSD as a potential therapeutic strategy in AML." (PMID 40796615, 2025). "Furthermore, we explored the role of CTSD in leukemia progression in vivo." (PMID 40796615, 2025). "To investigate the role of CTSD in AML, we first used small interfering RNA (siRNA) to silence CTSD expression in U937, MV4-11, and MOLM-13 leukemia cell lines." (PMID 40796615, 2025).
malaria (5 papers, 2011 to 2022). Malaria is a serious and sometimes fatal disease caused by a parasite that commonly infects a certain type of mosquito which feeds on humans. "Based on these results, we designed and synthesized a selective peptidomimetic compound and tested its inhibition of PbPM4, seven FV plasmepsins from human malaria parasites, and human cathepsin D (hcatD)." (PMID 26510189, 2015). "Despite these headways, the major obstacle in targeting PM is the structural homogeneity among its members and to human Cathepsin D. The incorporation of CADD techniques described in the study at early stages of drug discovery could help in selective inhibition to augment malaria chemotherapy." (PMID 36432016, 2022). "Out of the six proteins, three were identified as showing increased levels (CRP, CSF1, LBP) in malaria patients compared to controls while the remaining three displayed decreased levels (CCL5, CTSD, SPARC)." (PMID 30442134, 2018). "Three proteins displayed lower protein levels in the malaria cases compared to the controls; anti-adhesive SPARC (also known as Osteonectin), cell migration chemoattractant CCL5 (also known as RANTES) and apoptotic CTSD." (PMID 30442134, 2018). "A paradoxical finding of our study was that the absence of cathepsin D leads to reduced processing, but does not impair either malaria specific IgG production or parasite clearance." (PMID 22053177, 2011).
prion disease (5 papers, 2008 to 2026). A transmissible disease that is caused by a protein that is able to induce abnormal folding of normal cellular proteins, leading to characteristic spongiform brain changes, which are associated with neuronal loss without an inflammatory response. "The possible role of cathepsin D in the development of prion diseases was demonstrated in interferon-α/β receptor knock-out mice showing decreased levels of disease-associated microglial cathepsin D and CD68 receptor, especially in white matter, which resulted in the slow disease progression." (PMID 34198733, 2021). "On the other hand a significant correlation between tissue pathology and volume of neuronal cathepsin D immunoreactive lysosomes was demonstrated emphasizing the role of cathepsin D in the pathogenesis of prion disease." (PMID 18426579, 2008).
psoriasis (5 papers, 2015 to 2024). An autoimmune condition characterized by red, well-delineated plaques with silvery scales that are usually on the extensor surfaces and scalp. "Similar to vitiligo, decreased levels of cathepsin D have been found in psoriasis and atopic dermatitis and have been linked to increased TNF-α levels." (PMID 38715599, 2024). "Other cathepsin family members, such as CTSS, CTSK, and CTSD, have been implicated in the pathology of psoriasis." (PMID 30642337, 2019). "Previous studies found that CTSD was highly expressed in psoriasis and traumatic wounds and suggested that CTSD played an important role in the epidermal barrier repair process and wound healing promotion." (PMID 39871835, 2024). "The cleavage reaction is mediated by Cathepsin D (CDSD), which also shows elevated expression in psoriasis lesions (FC = 1.56; P = 4.61 × 10−38)." (PMID 25883770, 2015). "CTSH was surrounded by CTSS, CTSD and other critical factors involved in complement and adhesion (e.g., C3 and ICAM1) in the psoriasis network, suggesting that it might trigger inflammatory responses by regulating the neighbors in the network." (PMID 30642337, 2019).
renal fibrosis (5 papers, 2016 to 2024). A final common manifestation of a wide variety of chronic kidney diseases characterized by glomerulosclerosis and tubulointerstitial fibrosis. "The inhibition of CTSD has been considered a new therapeutic approach to reduce renal fibrosis and slow the progression of CKD induced by obstructive nephropathy." (PMID 29950996, 2018). "In summary, here we report for the first time the distribution of CtsD and B in human renal disease and show the effect of their inhibition in two mouse models of renal fibrosis." (PMID 26831567, 2016). "In addition, enhanced collagen degradation through lysosomal recycling impairment was shown in renal fibrosis by inhibition of Cathepsin D." (PMID 31941499, 2020). "CTSD was also indicated to play an important role in renal fibrosis." (PMID 29950996, 2018). "Taken together these results suggest that inhibition of lysosomal proteases, such as CtsD, could be a new therapeutic approach to reduce renal fibrosis and slow progression of CKD." (PMID 26831567, 2016). "Therefore, the decrease of cathepsin D levels in ClC-5–deleted cells may also contribute to the tubular dysfunction observed in DD patients and halt the recovery after damage, thereby further promoting renal fibrosis." (PMID 38670633, 2024). "And some of these proteins like CTSD, ATF3, Wnt5a were reported play important roles in renal fibrosis or other kidney disease." (PMID 28912732, 2017). "And some of these proteins like CTSD, ATF3, WNT5A were reported play important roles in renal fibrosis or other renal disease." (PMID 28912732, 2017). "Furthermore, out results suggested that TCONS_00088786 (neighbor of CtsD) and TCONS_01496394 (neighbor of ATF3) may be critically involved in renal fibrosis, with being regulated by TGF-β/Smad signaling, forming a feedback loop to regulate renal fibrosis." (PMID 28912732, 2017).
retinal degeneration (5 papers, 2015 to 2023). Degeneration of the retina. "In the Royal College of Surgeons rat model of retinal degeneration, the release of Cathepsin D from the RPE cells is associated with the fragility of lysosomal membranes." (PMID 32815311, 2020). "For example, the mcd/mcd mouse model that expresses an inactive form of cathepsin D (the CLN10 gene causing congenital NCL), leading to a major block in phagosome degradation in the RPE, exhibits a severe retinal degeneration." (PMID 26450516, 2015). "A single intravitreal injection of recombinant CTSD into P7 and P14 CLN10 mutant mice partially attenuated lysosomal dysfunction and reduced reactive microgliosis but failed to prevent the photoreceptor loss and retinal degeneration." (PMID 35509995, 2022). "Of interest in this context is that CLN10 patients carrying mutations in the CTSD gene that impair, but not completely abolish, the enzymatic activity of CTSD present with an infantile or juvenile disease onset and progressive retinal degeneration." (PMID 33800998, 2021). "Here, we performed an in-depth analysis of retinal degeneration at the molecular and cellular levels in mice lacking the lysosomal aspartyl protease cathepsin D, an animal model of congenital CLN10 disease." (PMID 33800998, 2021). "Moreover, we recently showed that intravitreally injected human recombinant pro-CTSD significantly reduced the amount of storage material in the Ctsd ko retina without, however, attenuating retinal degeneration in the treated animals." (PMID 33800998, 2021). "In striking contrast, a brain-directed AAV-mediated expression of cathepsin D in a CLN10 mouse model prevented the accumulation of ceroid lipofuscin, the activation of microglia, and neurodegeneration in brain tissues, but not the rapidly progressing retinal degeneration." (PMID 35509995, 2022).
acute kidney injury (4 papers, 2017 to 2022). Sudden and sustained deterioration of the kidney function characterized by decreased glomerular filtration rate, increased serum creatinine or oliguria. "Further analyses that included vancomycin as an additional potential stressor revealed a common match for genes encoding cathepsin A, cathepsin C, cathepsin D and cathepsin S and an association of cathepsins with the lysosomal pathway, kidney disease and acute kidney injury." (PMID 35516525, 2022). "For example, CtsD was upregulated in damaged tubular cells in nephrotoxic and ischemia reperfusion induced acute kidney injury." (PMID 28912732, 2017).
bladder cancer (4 papers, 2014 to 2025). "Determination of cathepsin D (Cat D) concentration in serum and urine may be useful in the diagnosis of bladder cancer." (PMID 25120717, 2014).
Cognitive impairment (4 papers, 2021 to 2025). Abnormal cognition is characterized by deficits in thinking, reasoning, or remembering. "However, since cognitive impairment, a typical symptom in patients with dementia, has been widely used as a standard for AD diagnosis, we examined the correlation between cognitive abilities and the level of plasma cathepsin D." (PMID 33445607, 2021).
dementia (4 papers, 2016 to 2023). Loss of intellectual abilities interfering with an individual's social and occupational functions. "Intriguingly, we observed down-regulation of the myelin-associated protein Cathepsin D in women with dementia while the rest of myelin proteins identified in that group were significantly upregulated." (PMID 26983404, 2016). "The level of plasma cathepsin D was negatively correlated with clinical dementia rating scale sum of boxes (CDR-SB) scores." (PMID 33445607, 2021). "Thus, more studies are needed in order to clarify the role of cathepsin D as a blood biomarker of dementias." (PMID 36142612, 2022). "In contrast, AD + CVD patients did not exhibit any change on the degradation ratio of the cathepsin D byproduct YLATASTMDHAR#, despite that increased level of peptide citrullination was detected for this byproduct in women with dementia." (PMID 26983404, 2016).